ENSG00000200112
Synonyms: LOC124900323
Gene: Small nucleolar RNA gene on chromosome 12 (115,852,648 to 115,852,718, reverse strand). Ensembl gene ENSG00000200112.
Gene Ontology:
Biological process: RNA processing
Cellular component: nucleolus
Homologues: Paralogues in human: SNORD56 (82% identical), SNORD56B (80% identical).